H19 (H19 imprinted maternally expressed transcript)
Diseases named in the same sentence as H19 in open-access papers (continued):
Sharing a sentence is not in itself a finding about the gene and the disease.
Stroke (continued). "Levels of H19 in the circulation of patients with IS have been positively correlated with the National Institute of Health Stroke Scale Scores of the patients in in three time points following stroke attack." (PMID 34867304, 2021). "The current study showed that circulating H19 levels within the first 24 h after the onset of a stroke have a sensitivity of 79.4% and a specificity of 80%." (PMID 33541284, 2021). "We concentrated on the expression pattern of H19 at different time points (i.e., 0–24, 24–48, and 48–72 h after stroke)." (PMID 33541284, 2021). "Further analysis indicated that H19 expression was found more often in IS patients than in the controls 0–24, 24–48, and 48–72 h after the onset of stroke (P < 0.001, P < 0.05, P < 0.01, respectively)." (PMID 33541284, 2021). "Our group has demonstrated for the first time that circulating lncRNA H19 levels were significantly higher in stroke patients compared with healthy controls." (PMID 33192490, 2020). "H19 inactivation in NSCs significantly attenuates motor and cognitive function after stroke in vivo." (PMID 32867041, 2020). "Our group reported that compared with healthy controls, circulating lncRNA H19 levels were upregulated in patients with stroke." (PMID 33192490, 2020). "The elimination of H19 revealed its involvement in the regulation of transcription, apoptosis, cell proliferation, and reaction to ischemia post-stroke." (PMID 33192490, 2020). "Circulating H19 levels, which were significantly higher in 36 stroke patients compared with 25 HCs, showed a positive correlation with NIHSS scores and tumor necrosis factor-α levels." (PMID 30967760, 2019). "Evaluation of these two parameters revealed that H19 levels were positively correlated with patient NIHSS scores within 3 hours from stroke onset (p<0.05)." (PMID 31170091, 2019). "This study found that H19 levels were elevated in the serum of stroke patients, as well as in the ischemic penumbra of rats with middle cerebral artery occlusion/reperfusion (MCAO/R) injury and neuronal cells with oxygen glucose deprivation (OGD)." (PMID 31170091, 2019). "It’s reported that increased H19 levels in stroke patients’ blood impaired neurological function and correlated with tumor necrosis factor-α (TNF-α) levels, which was further verified in animal model." (PMID 29651234, 2018). "Additionally, the prognosis of stroke patients has shown positive correlations with the expression levels of H19 and TNF‐α in the blood, suggesting their potential as diagnostic indicators with high sensitivity and specificity." (PMID 39049714, 2024). "The level of H19 in the circulation has been reported to increase in patients with IS and are positively correlated with the National Institute of Health Stroke Scale Scores within 3 h after stroke onset and 7 days after thrombolytic treatment." (PMID 35946958, 2022). "H19 expression in neutrophils was significantly increased in patients with stroke (p < 0.05)." (PMID 35322553, 2022). "Lateral ventricle injection of small interfering RNA H19 reduced infarct volume and cerebral edema, decreased pro-inflammatory cytokine levels, and increased plasma anti-inflammatory cytokine interleukin-10 levels 24 h after stroke." (PMID 36275741, 2022). "H19 expression levels in IS patients were compared to levels of controls 0–24 h (4.51 ± 0.88 vs 0.96 ± 0.12), 24–48 h (7.12 ± 1.53 vs 2.73 ± 1.19), and 48–72 h (6.38 ± 1.36 vs 1.84 ± 0.36) after stroke." (PMID 33541284, 2021). "ROC curves showed that H19 expression within the first 24 h from stroke onset might serve as a biomarker for the early diagnosis of IS with 79.49% sensitivity and 80.00% specificity." (PMID 33541284, 2021). "H19 expression was significantly upregulated in IS and remained high for 72 h after stroke." (PMID 33541284, 2021). "lncRNA H19 has also been shown to make a significant contribution to stroke pathology." (PMID 33192490, 2020).
Stroke (continued). "Altogether, these studies support the concept that pharmaceutical intervention regulating H19 expression may be therapeutically beneficial in stroke recovery." (PMID 33192490, 2020). "Intracerebroventricular injection of H19 siRNA reduces infarct volume and brain edema, decreases tumor necrosis factor-α and interleukin-1β levels in brain tissue and plasma, and increases plasma interleukin-10 levels 24 h post-stroke." (PMID 30967760, 2019). "Interestingly, our study hints that miRNA-23a, miRNA-99a, and lncRNA H19 could be the possible mediators responsible for the effect of neutrophils on stroke outcomes after thrombolysis." (PMID 36278201, 2022). "Interestingly, loss of H19 at the onset of ischemia in a rat MCAO model prevented the induction of TNF-α, IL-1β and IL-6 concentrations in plasma and brain tissue within 24 h after stroke onset." (PMID 35946958, 2022). "More accurate findings could be observed by using larger sample sizes and by taking blood samples during the first few hours after a stroke to determine whether H19 SNP affects H19 expression and whether NIHSS has a significant correlation with H19 expression level." (PMID 33541284, 2021). "Interestingly, we observed that upregulated H19 remained high 72 h after a stroke." (PMID 33541284, 2021). "Notably, functional rehabilitation following stroke was retarded when H19 was blocked in NSCs." (PMID 33192490, 2020). "H19 and C1QTNF6 upregulation, as well as miR‐29b downregulation, was detected in leukocytes of patients with stroke." (PMID 35322553, 2022). "Many aberrant lncRNA expressions such as MEG3, H19, MALAT1, ZFAS1, GAS5, LincRNA-EPS, SHNG16, etc. were suggested to regulate cell apoptosis, angiogenesis, inflammation and cell death in different brain cell types after stroke." (PMID 32867041, 2020). "Knockdown of H19 by siRNA in MCAO rats reduced brain infarct as well as TNF-α and interleukin-1β (IL-1β), and it increased plasma interleukin-10 (IL-10) concentrations 24 h after stroke." (PMID 29651234, 2018).
thyroid cancer (24 papers, 2018 to 2025). "Recently, high expression of the lncRNA H19 in thyroid carcinoma was associated with increased levels of T cells, B cells, dendritic cells, neutrophils, and macrophage infiltration, as well as increased immune gene signatures." (PMID 41154428, 2025). "In addition, long non-coding RNA H19, which is known for its metastatic property in several tumors, has also been found to be implicated in thyroid cancer." (PMID 29561759, 2018). "In addition, the study linked H19 overexpression to poor prognosis in patients with thyroid cancer." (PMID 32596158, 2020). "H19 is generally upregulated in thyroid cancer tissues, and silencing H19 can increase the expression of the pro-apoptotic proteins, e.g., Bax and caspase-3, and decrease the expression of the anti-apoptotic protein, Bcl-2." (PMID 41154428, 2025). "Studies in thyroid cancer cell lines show that silencing H19 decreased cell viability and increased apoptosis in these cells, and correlated with decreased levels of phosphorylation of PI3K and AKT, suggesting decreased activity of the pathway." (PMID 41154428, 2025). "Long non-coding RNA H19 is upregulated in thyroid cancer tissues and is an important contributor to the promotion of cancer cell proliferation and survival in thyroid cancer cells, at least in part by inducing PI3K/AKT signaling." (PMID 41154428, 2025). "This implies that H19 functions as an oncogene in thyroid cancer, enabling the signaling of the PI3K/AKT pathway to promote tumor cell growth and support resistance to cell death." (PMID 41154428, 2025). "In short, targeting H19 or the PI3K/AKT signaling as a therapeutic approach for the management of thyroid cancer is exciting." (PMID 41154428, 2025). "In the case of H19, estradiol (E2) promotes H19 transcription through estrogen receptor β, which induces stem-like properties in thyroid cancer." (PMID 38095719, 2024). "Recent studies have shown that lncRNAs that interact with estrogen receptors, such as Metastasis-Associated Lung Adenocarcinoma Transcript 1 (MALAT1), and lncRNA-H19 (H19), are enhanced by estrogen receptors in lung and thyroid cancers." (PMID 38095719, 2024). "Previous findings in the literature have described the low expression of the H19 gene and its products in thyroid cancer, which contradicts the high expression of this sequence in the multinodular goiter samples used in this study." (PMID 35594253, 2022). "H19 knockout inhibited cell viability and induced apoptosis of thyroid cancer cells by prominently increasing the expression of Bax and caspase three and repressing the expression of Bcl-2." (PMID 34977037, 2021). "H19 is involved in the expression of members of the PI3K/Akt signaling pathway to regulate thyroid cancer progression." (PMID 34977037, 2021). "Controlling for another ncRNA surveyed in this study, the higher H19 and lower let-7a along with tumor size, stage and lymph node metastasis were confirmed as the independent prognostic factors of thyroid cancer." (PMID 33158279, 2020). "The dysregulation of H19 in thyroid cancer is subject of controversy since the down-regulation was reported in FTC and PTC, while the overexpression is reported in PTC, ATC and PTC/PTC stem cells (PTCSCs)." (PMID 33158279, 2020). "lncRNA H19 has been widely studied in different thyroid cancer cohorts that showed controversial prognostic results." (PMID 33158279, 2020). "Ultimately, targeting H19 may represent a novel therapeutic approach to promote apoptosis and inhibit tumor growth in thyroid cancer by inhibiting the activation of the PI3K/AKT signaling axis." (PMID 41154428, 2025). "The long non-coding RNA H19 regulates the viability of thyroid cancer cells, primarily via the mechanism of regulating the PI3K/AKT survival signaling axis, and the knockdown of H19 has been shown to decrease the viability of thyroid cancer cells at the cell level and to increase apoptosis." (PMID 41154428, 2025).
thyroid cancer (continued). "H19 expression is also higher in thyroid cancer tissue than in normal tissue, which may promote the migration of thyroid cancer cells." (PMID 35642209, 2022). "In thyroid cancer, H19 may be a suppressor gene, and its overexpression inhibits cell viability, migration, and invasion but promotes cell apoptosis." (PMID 34977037, 2021). "Moreover, the authors found that the PI3K/Akt signaling pathway is involved in the process by which H19 silencing inhibits thyroid cancer cell viability and induces apoptosis with significantly decreased phosphorylated PI3K and phosphorylated Akt." (PMID 34977037, 2021). "H19 is over six-fold overexpressed in thyroid cancer tissues compared with adjacent normal tissues." (PMID 34977037, 2021). "H19 can promote invasion and metastasis of thyroid cancer cells in vivo and in vitro." (PMID 32596158, 2020). "Given the functional studies performed in these reports, the oncogenic nature of H19 in thyroid cancer is more conceivable since H19 knockdown resulted in the suppression of proliferation, migration, and invasion in ATC cells in vitro and inhibited tumorigenesis and metastasis in vivo." (PMID 33158279, 2020). "Moreover, the depletion of H19 was shown to suppress the sphere formation ability, collectively suggest that H19 acts as an oncogene in thyroid cancer." (PMID 33158279, 2020). "Because of the role of H19 in lung metastases in other tumor types, and the importance of distant metastases in thyroid cancer, we developed an experimental metastasis model using an injection approach in a murine model of ATC to study tumor growth and metastasis." (PMID 31299871, 2019). "Furthermore, the Kaplan–Meier survival analysis demonstrated that high H19 levels were a strong indicator for poor overall survival of thyroid cancers in TCGA database, suggesting a remarkably unfavorable prognosis and shorter lifespan." (PMID 30389909, 2018). "Furthermore, this study focused on the role exerted by H19 in thyroid cancer cells that were treated with deacetylase inhibitors." (PMID 29561759, 2018). "Interestingly, H19 in thyroid cancer positively correlated with CD8+ T cells, CD4+ T cells, B cells, and other infiltrates, which indicates that in some contexts, lncRNA-miRNA interactions may increase the recruitment of immune cells." (PMID 41154428, 2025). "Thus far, few studies have examined the relationship between H19 and thyroid cancer." (PMID 32596158, 2020). "However, rs7958904 may alter HOTAIR’s secondary structure (in silico CRC-related study), H19 rs2839698 is linked to higher risk in digestive system cancers, and PTCSC3 rs944289 reduces promoter activity and PTCSC3 expression in thyroid carcinoma (GWAS Catalog: GCST000335)." (PMID 41463069, 2025). "Sedaghati summarized the dysregulated and functional LncRNAs in thyroid cancer, including 28 upregulated LncRNAs, such as ANRIL, BANCR, H19, HOTAIR, MALAT1, and NEAT1, and 22 downregulated LncRNAs, including GAS5, NAMA, PTCSC2, and PTCSC3." (PMID 37874339, 2024). "More importantly, some non-coding RNAs were considered as the known prognosis biomarkers in thyroid cancer, such as let-7a, LINC-PINT, H19, MALAT1 and HOXA-AS2." (PMID 37153003, 2023). "In thyroid cancer, several lncRNAs, such as MALAT1, H19, BANCR, and HOTAIR have been identified as contributing factors to tumor development, and used as novel biomarkers for early diagnosis or treatment." (PMID 34404767, 2021). "In thyroid cancer, several lncRNAs, such as MALAT1, H19, BANCR, HOTAIR have been identified as contributing factors to the development of cancer." (PMID 34404767, 2021). "In accordance, downregulation of H19 in SW579 and TPC-1 thyroid cancer cell lines decreased cell viability, migration and invasion." (PMID 34526543, 2021). "Deacetylase inhibitors reduced cell viability, restored NIS and H19, and suppressed the oncogenes HMGA2 and TTF1 in thyroid cancer cells." (PMID 29561759, 2018).
thyroid cancer (continued). "Therefore, there is evidence supporting the conclusion that H19 acts as an oncogene in thyroid cancer, at least in part via activation of the PI3K/AKT pathway, in order to enhance the pro-survival properties of thyroid cancer cells." (PMID 41154428, 2025). "Furthermore, H19 has been shown to inhibit Insulin receptor Substrate 1(IRS-1), leading to reduction of cell viability, migration, and invasion in thyroid cancer cells." (PMID 29561759, 2018).
non-small cell lung carcinoma (23 papers, 2013 to 2026). A group of at least three distinct histological types of lung cancer, including non-small cell squamous cell carcinoma, adenocarcinoma, and large cell carcinoma. "Studies have shown that β-Elemene can enhance the sensitivity of EGFR-mutated non-small cell lung cancer to erlotinib by upregulating lncRNA H19 and inducing ferroptosis, providing a new approach to overcoming drug resistance in TNBC." (PMID 40454580, 2025). "By targeting tumor suppressors, the lncRNA H19-derived miR-675-5p is linked to the advancement of non-small cell lung cancer (NSCLC)." (PMID 37373137, 2023). "Among cancers, such as liver cancer, colon cancer, non-small cell lung cancer, and oral cancer, H19 is associated with the progression of these cancers by altering the level of the component of the MAPK signaling pathway." (PMID 34977037, 2021). "The arising results, concerning miR-29a-3p in exosomes and lncRNA H19 in cfRNA, widen the horizons for identifying and exploiting promising biomarkers in non-small-cell lung cancer." (PMID 39594687, 2024). "Currently, the impact of H19 on resistance to therapeutic option is mainly focused on non-small cell lung cancer (NSCLC)." (PMID 36246634, 2022). "At present, LncRNA H19 in combination with chemotherapy has been shown to improve in vitro treatment efficacy against non-small-cell lung cancer." (PMID 33402118, 2021). "Upregulation of H19 promotes cell proliferation correlates with poor prognosis in non-small-cell lung cancer." (PMID 27322142, 2016). "In addition, the observed increase in histone acetylation levels in human non-small cell lung cancer cells and human lymphoma cells can promote the expression of DNMT1, cause hypermethylation at the ICR binding site of CTCF-H19/IGF2, and reduce the occupancy of CTCF at the ICR of H19/IGF2." (PMID 38584203, 2024). "Previous evidence had identified BET family proteins as regulators of integrin signaling in triple-negative breast cancer and non-small cell lung cancer, but the contribution of non-coding RNAs such as H19 to this regulatory axis was not explored." (PMID 40407591, 2025).